LINC01574 (long independently transcribed non-coding RNA 1574)
Synonyms: HI-LNC12; TCONS_00009551
Gene: Long non-coding RNA gene on chromosome 5 (176,743,104 to 176,791,252, forward strand). Ensembl gene ENSG00000248859.
Diseases named in the same sentence as LINC01574 in open-access papers:
LINC01574 is named in the same sentence as 2 diseases in open-access papers, as found by Europe PMC text mining. Sharing a sentence is not in itself a finding about the gene and the disease. The quoted sentences say what the papers report.
glioblastoma multiforme (1 paper, 2024). "Through our investigation, we identified four promising graphene therapy–related long non-coding RNAs (AC011405.1, HOXC13-AS, LINC01127 and LINC01574) that could be utilized for treating glioblastoma multiforme patients." (PMID 38162904, 2024).
tumor (1 paper, 2022). "H&E staining and immunohistochemistry showed that LINC01574 knockdown further increased tumor cell death and decreased the Ki-67 protein level in subcutaneous BC tissues." (PMID 35935583, 2022). "Concomitantly, LINC01574 was also highly expressed in BC tumor tissue than in paired normal tissues." (PMID 35935583, 2022). "Initially, the LINC01574 expression in BC cell lines and BC tumor tissues was analyzed, and we found that LINC01574 was significantly upregulated in BC cells, especially in MDA-MB-231 and MDA-MB-468." (PMID 35935583, 2022). "In summary, our data proved that miR-6745 was regulated by LINC01574 and may play a role as a tumor suppressor gene in the development and progression of BC." (PMID 35935583, 2022). "Next, the correlation between LINC01574 levels and clinical characteristics was analyzed; we found that the expression of LINC01574 in T2, III, and NI/2 BC tumor tissues was remarkably higher than that in T1, I/II, and N0 BC tumor tissues, respectively." (PMID 35935583, 2022).